LURAP1L (leucine rich adaptor protein 1 like)
Synonyms: C9orf150; HYST0841; MGC46502; FLJ38505; bA3L8.2; LRAP35b
Tractability: No criterion of Open Targets' tractability assessment is met for any kind of drug.
Gene: Protein-coding gene on chromosome 9 (12,775,020 to 12,823,060, forward strand). Ensembl gene ENSG00000153714.
Subcellular location (Human Protein Atlas): Nucleoli; Nucleoplasm
Gene Ontology:
Molecular function: protein binding
Biological process: positive regulation of canonical NF-kappaB signal transduction
Genetic constraint (gnomAD): Loss-of-function variants: 12 observed, 13.89 expected, observed/expected ratio (o/e) 0.86, 90% interval 0.55 to 1.4. The upper end of that interval is the gene's LOEUF score, 1.4, which puts it in group 5 of 6, group 1 being the genes least tolerant of losing a copy. Missense variants: 374 observed, 295.65 expected, observed/expected ratio (o/e) 1.26, 90% interval 1.16 to 1.38. Synonymous variants: 138 observed, 121.38 expected, observed/expected ratio (o/e) 1.14, 90% interval 0.99 to 1.31.
Homologues: Orthologues: chimpanzee LURAP1L (99% identical), macaque LURAP1L (97% identical), dog LURAP1L (94% identical), guinea pig LURAP1L (91% identical), pig LURAP1L (91% identical), mouse Lurap1l (88% identical), rabbit LURAP1L (88% identical), rat Lurap1l (88% identical), tropical clawed frog lurap1l (54% identical). Paralogues in human: LURAP1 (32% identical).
Diseases named in the same sentence as LURAP1L in open-access papers:
LURAP1L is named in the same sentence as 10 diseases in open-access papers, as found by Europe PMC text mining. Sharing a sentence is not in itself a finding about the gene and the disease. The quoted sentences say what the papers report.
periodontitis (2 papers, 2024). An acute or chronic inflammatory process that affects the tissues that surround and support the teeth. "The ANN diagnostic model comprising four key genes—SLC1A5, SLC2A14, LURAP1L, and HERPUD1—demonstrated a high predictive efficacy for periodontitis with an AUC of 0.928 in the dataset." (PMID 38802844, 2024). "The ferroptosis-related genes identified in this study, including SLC1A5, SLC2A14, LURAP1L, and HERPUD1, may serve as novel diagnostic and therapeutic targets for periodontitis." (PMID 38802844, 2024). "Secondly, our study identified six transcripts that are tissue biomarkers for periodontitis (ALOX12B, BNIP3, CEBPG, LURAP1L, RGS4, and TFAP2C) potentially significant for periodontitis using three machine learning methods: LASSO, SVM, and RF." (PMID 39045324, 2024). "LURAP1L and RGS4 showed significant overexpression, whereas ALOX12B, BNIP3, CEBPG, and TFAP2C were notably underexpressed in periodontitis." (PMID 39045324, 2024). "The ferroptosis-related genes SLC1A5, SLC2A14, LURAP1L, and HERPUD1 may serve as novel biomarkers for the diagnosis of periodontitis." (PMID 38802844, 2024). "Based on this, our study hypothesizes that ferroptosis-related genes, including SLC1A5, SLC2A14, LURAP1L, and HERPUD1, could be novel biomarkers for periodontitis." (PMID 38802844, 2024). "Subsequently, through protein–protein interaction networks and multi-dataset machine learning algorithms, we further narrowed down these candidates to four key ferroptosis-related genes differentially expressed in periodontitis, namely SLC1A5, SLC2A14, LURAP1L, and HERPUD1." (PMID 38802844, 2024). "The results derived from the three machine learning methods were intersected and illustrated in a Venn diagram, revealing six transcriptional biomarkers critical for differentiating periodontitis tissues from healthy tissues: ALOX12B, BNIP3, CEBPG, LURAP1L, RGS4, and TFAP2C." (PMID 39045324, 2024).
asthma (1 paper, 2022). "LURAP1L gene expression was found significantly increased in the CD4+ T-cells of obese compared to normal-weighted children with asthma." (PMID 35910207, 2022).
COVID-19 (1 paper, 2022). A disease caused by infection with severe acute respiratory syndrome coronavirus 2. "One study showed that LURAP1L was among genes with altered gene expression in lung tissue of deceased COVID-19 patients that could be targeted with the anti-inflammatory activities of glucocorticoid drugs." (PMID 35910207, 2022).
juvenile idiopathic arthritis (1 paper, 2022). Juvenile idiopathic arthritis (JIA) is the term used to describe a group of inflammatory articular disorders of unknown cause that begin before the age of 16 and last over 6 weeks. "Previous GWA studies identified suggestive associations of LURAP1L genetic variants with juvenile idiopathic arthritis and pulmonary function in smokers." (PMID 35910207, 2022).
melanoma (1 paper, 2023). A malignant, usually aggressive tumor composed of atypical, neoplastic melanocytes. "MAP3K5, LURAP1L, HMOX1 might serve as negative risk factor for prognosis of osteosarcoma or melanoma." (PMID 36899330, 2023).
meningioma (1 paper, 2016). A generally slow growing tumor attached to the dura mater. "Among genes that were higher expressed in meningiomas from females were rhotekin 2 (RTKN2), neuritin 1 (NRN1), small nucleolar RNA, C/D box 114–26 (SNORD114-26), and leucine rich adaptor protein 1-like (LURAP1L)." (PMID 27096627, 2016).
osteosarcoma (1 paper, 2023). A usually aggressive malignant bone-forming mesenchymal neoplasm, predominantly affecting adolescents and young adults. "Five ferroptosis-associated genes (MUC1, MAP3K5, LURAP1L, HMOX1, and BNIP3) correlated with the prognosis of osteosarcoma were screened for the construction of the risk score model." (PMID 36899330, 2023). "MAP3K5, LURAP1L, HMOX1 and BNIP3 expression levels were markedly decreased in the osteosarcoma cells compared with the normal human osteoblast hFOB1.19 cells, they are negatively related with the riskscore." (PMID 36899330, 2023).
prostate carcinoma (1 paper, 2016). A carcinoma that arises from epithelial cells of the prostate gland. "In prostate cancer cell line PC-3, gene silencing of Toll-like receptor-9 (TLR9), reversed migration and invasiveness and resulted in downregulation of a number of genes including LURAP1L." (PMID 27096627, 2016).
cancer (1 paper, 2023). A tumor composed of atypical neoplastic, often pleomorphic cells that invade other tissues. "On the contrary, knockdown of MAP3K5, LURAP1L, BNIP3 and HMOX1 enhanced cancer cell migration." (PMID 36899330, 2023).
tumor (1 paper, 2021). "Six overall survival associated genes (ENPP2, ULK1, CP, LURAP1L, HIC1, AKR1C1) were selected to build survival model, of which hub gene AKR1C1 was with high expression and low ferroptosis level in NSCLC tumor." (PMID 34702254, 2021).